PDIA4 (protein disulfide isomerase family A member 4)
Diseases named in the same sentence as PDIA4 in open-access papers (continued):
Sharing a sentence is not in itself a finding about the gene and the disease.
cancer (26 papers, 2016 to 2025). A tumor composed of atypical neoplastic, often pleomorphic cells that invade other tissues. "The second μ-17-specific cancer-associated module comprises endoplasmic reticulum (ER) molecular chaperones (PDIA4, PDIA6, GANAB) and heat shock proteins (HYOU1, HSPA5, DNAJB11)." (PMID 41373892, 2025). "Increased expression of PDIA4 was observed in various types of cancer, while the detailed mechanisms are in deficiency." (PMID 36906674, 2023). "The results showed that the unfolded proteins HSPA5, HYOU1, and PDIA4 were associated with survivability in cancer, and HSPA5 was positively and significantly correlated with CD47, and induced by CD47 in OSCC cells lines." (PMID 35678681, 2022). "Several key proteins interacting with ATF4 such as NRF2, GPX4, SLC7A11, PDIA4 have been suggested as mediators of the role ATF4 plays in preventing ferroptosis in various cancer models." (PMID 40667288, 2025). "Together, these findings establish that DNAJB12, DNAJB14, and SGTA are required for PDIA4 reflux to the cytosol, where it binds caspase-3 and promotes cancer cell resistance." (PMID 41120732, 2025). "To investigate the nature of this interaction, we silenced PDIA4 and assayed the activity of caspase-3 in cells pretreated with ER stress inducers or anti-cancer drugs." (PMID 41120732, 2025). "The potential of PDIA4 as a prognostic marker has been investigated across various types of cancers." (PMID 41185082, 2025). "Protein disulfide isomerase family A member 4 (PDIA4), a member of the protein disulfide isomerase family, has been associated with the progression of cancer." (PMID 41185082, 2025). "PDIA4, a member of the PDI family, is implicated in the development of various diseases, such as cancer, diabetic kidney disease, and infectious diseases." (PMID 41185082, 2025). "Hypoxia, a hallmark of cancer, inhibited QKI expression which controlled the biogenesis of circ_0001766 via back-splicing of PDIA4 exons 2 and 3 in CRC." (PMID 40263288, 2025). "PDIA4 is also involved in maintaining redox homeostasis in various cells, including mouse embryos and cancer cells." (PMID 37958534, 2023). "A growing body of evidence demonstrated that aberrant PDIA4 expression level and its potential mechanisms participate in the development of numerous types of cancer, including GBM." (PMID 38159261, 2023). "Overexpression of PDIA4 is observed in cisplatin-resistant non-small cell lung cancer and emerges as a novel regulator of cancer growth." (PMID 36906674, 2023). "PDIA4 is able to interact with activated platelet, enhance DNA repair machinery and induce drug-resistance in cancers." (PMID 36003400, 2022). "PDIA4 belongs to the protein disulfide isomerase family, which is a key step in protein folding in the endoplasmic reticulum, and is involved in the formation of inter-protein disulfide bonds, which plays a significant role in promoting cancer." (PMID 38167446, 2024). "Furthermore, the knockdown of PDIA4 expression in cancer cells interferes with cell growth, cell apoptosis, and increased chemotherapy sensitivity." (PMID 36997943, 2023). "PDIA4 was significantly upregulated in most cancers and was most significantly upregulated in GBM." (PMID 36997943, 2023). "Moreover, PDIA4 protein has been found to be secreted in the serum of Chinese adults with metabolic syndrome which elicit its potential extracellular role in cancer." (PMID 35965326, 2022). "For example, protein disulfide isomerase family A member 4, which is encoded by a gene (PDIA4) whose expression is directly correlated with TGIF1, can disrupt the DNA repair mechanism, thereby promoting the proliferation and metastasis of cancer cells." (PMID 35569122, 2022). "Some researchers also concentrated on the roles of PDIA4 in other human cancers." (PMID 33159506, 2021).
cancer (continued). "Interestingly, the reported functions of PDIA4 in cancer are highly context-dependent." (PMID 41185082, 2025). "Also pan-cancer analysis of PDIA4 was performed utilizing the GEPIA2 database." (PMID 38167446, 2024). "Multiple studies have determined that PDIA4 is overexpressed in various cancer cell lines and clinical samples, and is highly associated with the clinical prognosis of cancer patients, which suggests that PDIA4 could be a vital biomarker and target for cancer treatment." (PMID 36997943, 2023). "Collectively, these findings position PDIA4 as a critical effector of ERCYS and highlight ERCYS as a central mechanism by which cancer cells neutralize apoptosis and acquire chemoresistance." (PMID 41120732, 2025). "An antibody specific for PDIA4 co-immunoprecipitated TAX1BP1, while an antibody specific for TAX1BP1 co-immunoprecipitated PDIA4, according to our findings, PDIA4 acted as a binding partner for TAX1BP1 in TNBC cells and cancer specimens." (PMID 38167446, 2024). "To further explore the role of CD47, HSPA5, HYOU1, and PDIA4 genes in cancer, we used the human protein atlas (HPA) database to analyze the expression of these target genes in cancer and their impact on the ability of cells to survive." (PMID 35678681, 2022). "The expression of PDIA3, PDIA4, PDIA6, ERP29, and TXNDC5 have also upregulated in most cancer types." (PMID 35965326, 2022). "The results found that HSPA5, HYOU1, and PDIA4 were involved in the IPA network and when highly expressed, mediated the survivability of cancer." (PMID 35678681, 2022). "Microarray data analysis has demonstrated the upregulation of several typical PDI members including PDIA1, PDIA3, PDIA4 and PDIA6 in multiple cancers such as breast, colorectal, liver, brain and prostate." (PMID 33742523, 2021). "In summary, cancer cells acquire chemoresistance by pre-activating the ER stress–dependent pro-survival mechanism ERCYS, which mediates cytosolic reflux of select ER-resident proteins, including PDIA4." (PMID 41120732, 2025). "Likewise, other PDI members namely PDIA3, PDIA4, and PDIA6 are also highly expressed in numerous cancer types including breast, thyroid, rectal, gastric and liver cancers." (PMID 35965326, 2022). "PDI family proteins, such as AGR2, PDI, PDIA3, PDIA4, and PDIA6 are reportedly upregulated in cancers, which are correlated with cancer progression and metastatic disease in pancreatic, kidney renal clear cell carcinoma (KIRC), ovarian cancers, glioblastoma and lung adenocarcinoma." (PMID 36202782, 2022). "Comparison of these selective PDIA1 inhibitors with E64FC26; a potent pan‐style inhibitor which inhibits; PDIA1, PDIA3, PDIA4, PDIA6 and TXNDC5, would give an indication as to whether inhibition of PDIA1 alone is sufficient for suppressing cancer cell growth." (PMID 33742523, 2021). "The P4HB (also known as PDIA1) and PDIA4, which were chosen from the six-gene signature, belong to the protein PDI protein family and have been proved to be related to ER stress activation in human cancers, especially the PERK signaling pathway." (PMID 34307339, 2021). "ENO1, GAPDH, NQO1, PDIA4, and PDIA6 may serve as potential targets for cancer therapy." (PMID 37955007, 2023). "Our data show a novel non-genetic mechanism to inhibit apoptosis and suggest PDIA4, DNAJB12/14, and SGTA as novel therapeutic targets to rescue apoptosis and inhibit proliferation in cancer cells." (PMID 41120732, 2025).
infection (5 papers, 2011 to 2023). The state of being infected such as from the introduction of a foreign agent such as serum, vaccine, antigenic substance or organism. "Using the function gain or loss method, PDIA4 was convincingly proven to be a host factor that facilitates the infection of LCMV in host cells." (PMID 38140584, 2023). "By detecting the viral titers of LCMV-MACV and LCMV-LASV in the supernatants of LCMV-MACV- or LCMV-LASV-infected PDIA4-KO A549 cells at 24 h.p.i., we verified that the genetic ablation of PDIA4 would affect the infection of LCMV-MACV and LCMV-LASV." (PMID 38140584, 2023). "This conclusion was based upon the fact that molecules such as BiP and PDIA4 had their mRNA levels significantly reduced in ATF6α knockout cells upon infection." (PMID 37434252, 2023). "According to KEGG pathway visualization PDIA4 is responsible for the loading of antigenic peptides into MHCI molecules in the endoplasmic reticulum for release at the site of the infection (Sasa04141)." (PMID 34135900, 2021). "Of the 3 inhibitors tested (DTNB, 16F16 and PACMA31) only 16F16, a cell permeable inhibitor that had been reported to inhibit the enzymatic activity of PDIA4, showed an inhibitory effect on HAstV-8 infection." (PMID 33396308, 2020). "In addition, the inhibition of PDIA4 also influenced the infection of a panel of LCMV-arenavirus chimeras." (PMID 38140584, 2023). "Altogether, these findings suggest that the activity of PDIA4 is relevant for HAstV-1 and -8 infection, but not for HAstV-2, consistent with the results obtained in the far-Western assays." (PMID 33396308, 2020).
metabolic disease (2 papers, 2017 to 2022). A congenital disorder (due to inherited enzyme abnormality) or acquired (due to failure of a metabolically important organ) disorder resulting from an abnormal metabolic process. "Previous clinical studies have found that the serum expression of PDIA4 from patients with metabolic disease is significantly higher than that of patients without metabolic disease, suggesting that PDIA4 has the potential as a new therapeutic target for metabolic disease or IR." (PMID 36619574, 2022).
neurodegenerative disease (2 papers, 2019 to 2025). A disorder of the central nervous system characterized by gradual and progressive loss of neural tissue and neurologic function. "PDIA4 is up-regulated in mouse models of brain neurodegenerative diseases involving protein misfolding." (PMID 30845169, 2019).
adenocarcinoma (1 paper, 2016). A common cancer characterized by the presence of malignant glandular cells. "Adenocarcinoma-dependent elevations in LRPPRC were associated with similar increases in STOML2 and PDIA4, which exhibited 2- and 2.3-fold increases in adenocarcinoma relative to control tissue, respectively." (PMID 27799870, 2016). "NANS, COPG1 and PDIA4 were all negatively associated with adenocarcinoma-dependent reductions in PTRF, which was generally decreased in adenocarcinoma compared to control tissue (89% of patients)." (PMID 27799870, 2016). "Consistent with our proteomic data, mRNA expression of APEX1, HYOU1, PDIA4, NANS, LRPPRC, EPRS and COPG1 were significantly (Mann–Whitney U < 0.05) higher in adenocarcinoma compared to control whereas mRNA abundance of HBG1, HBG2, HBD, and PTRF were significantly (Mann–Whitney U < 0.05) lower." (PMID 27799870, 2016).
neurological disorders (1 paper, 2025). "Additionally, the ERS-related proteins were downregulated following anti-TNF-α and anti-IL-1β treatment, including those implicated in neurological disorders such as HYOU1, PDIA4, and PDIA3." (PMID 40338234, 2025).
PDIA4 also shares sentences with these, for which no sentence is quoted: melanoma (2 papers); virus infection (2); atherosclerosis (1); cardiovascular disease (1); clear cell ovarian carcinoma (1); congenital heart disease (1); COVID-19 (1); ER-stress (1); esophageal squamous cell carcinoma (1); Glucose intolerance (1); Hypertension (1); liver cancer (1); lymphomatous (1); MALT lymphoma (1); mesothelioma (1); myopathy (1); oral squamous cell carcinoma (1); preeclampsia (1); prostate adenocarcinoma (1); protein misfolding diseases (1); serous ovarian cancer (1); triple-negative breast carcinoma (1); type 2 diabetes mellitus (1); uterine corpus endometrial carcinoma (1); vitiligo (1).